IL6 (interleukin 6)
Diseases named in the same sentence as IL6 in open-access papers (continued):
Sharing a sentence is not in itself a finding about the gene and the disease.
Insulin resistance (continued). "The level of IL6 is increased in obese persons, revealing that IL6 is the major contributor to insulin resistance in diabetic conditions." (PMID 33490239, 2020). "In high fat diet fed obese mice, activated hepatic IL-6 signalling is accompanied by systemic and local insulin resistance, which can be reversed by neutralization of IL-6." (PMID 32555600, 2020). "The interruption of IL-6 signaling plays an important role in the process of insulin resistance and the pathogenesis of T2DM." (PMID 32655424, 2020). "The Il-6 was only related to insulin resistance (IR), which was evaluated through the HOMA-IR index." (PMID 32694929, 2020). "The persistent increase in chemokines and inflammatory cytokines such as TNF-α, INF-γ, and IL-6 leads to progression of insulin resistance in one hand and of DNP to end-stage renal disease and kidney failure on the other." (PMID 33442388, 2020). "Recent experimental evidence has shown an increased inflammatory potential of adipose tissue in aged animals by overproduction of interleukin 6 (IL-6), IL-8, IL-1β, and tumor necrosis factor α (TNF-α) causing insulin resistance." (PMID 31900232, 2020). "Hyperglycemia results in a high level of IL-6, and treatment with IL-6 induces hyperglycemia and insulin resistance." (PMID 32796637, 2020). "In mammals, interleukin-6 (IL6) and tumor necrosis factor have been proven to induce hepatic insulin resistance through the suppression of the cytokine signaling (SOCS3) pathway." (PMID 32754117, 2020). "In this way, elevated IL-6 and TNF-α serum levels can lead to insulin resistance and the occurrence of loss of muscle mass and function." (PMID 32399298, 2020). "RA patients with ε2ε3 genotype are associated with lower levels of TNF-α, IL-6, resistin, visfatin, and CVD risk, while RA patients with ε3ε4 genotype exhibited higher levels of LDL-C, insulin resistance, and higher CVD risks." (PMID 33297350, 2020). "In contrast, interleukin-6 was reduced, with both sources of choline compared to baseline, while eggs also had an effect on lowering C-reactive protein, insulin, and insulin resistance compared to baseline." (PMID 33066009, 2020). "Adiponectin, leptin, resistin, tumor necrosis factor alpha (TNF-α) and interleukin 6 (IL-6) are produced, being tied to insulin resistance and hyperinsulinemia, thus directly or indirectly affecting AD risk." (PMID 32503113, 2020). "In particular, IL-6 and TNFα seem to directly interfere with the normal transmission of insulin signals, promoting the onset of insulin resistance and later the onset of type 2 diabetes." (PMID 33330284, 2020). "Creeping fat is among the major sources of the proinflammatory cytokine IL-6 seen in IBD patients, and augmented circulating levels of IL-6 in diet-induced obese mice promote the development of insulin resistance and type 2 diabetes." (PMID 33334069, 2020). "Açaí reduced blood glucose, insulin resistance, leptin and IL-6 levels, lipid profile, and vascular dysfunction." (PMID 32565751, 2020). "In adipose tissue, IL-6 and TNF-α were the activators of the NF-κB pathway, linked to insulin resistance in obesity." (PMID 33060792, 2020). "Some studies suggest that TNF-α and IL-6 interact to interfere with insulin signal transduction, which leads to insulin resistance and eventually to the occurrence of GDM." (PMID 32280713, 2020). "Another possible modulator of inflammation in GDM is insulin resistance, which is linked to increased levels of hs-CRP, IL-6, and TNF-α." (PMID 33081175, 2020). "The resultant increased appetite further perpetuates the leptin and insulin resistance and IL-6 mediated inflammation." (PMID 33202598, 2020). "For example, IL-6 activates AMPK signaling during short-term exposure to increase insulin sensitivity, and chronic IL-6 exposure triggers insulin resistance." (PMID 32961822, 2020).
Insulin resistance (continued). "The results reflected a decrease in insulin resistance and inflammatory markers TNF-alpha (tumor necrosis factor-alpha) and IL-6 (interleukin-6) associated with it." (PMID 33457118, 2020). "We observed lower serum levels of IL-6, suggesting moderate inflammation and immune response, and lower fasting insulin levels in serum, indicating the amelioration of insulin resistance, in the CR group compared with the ad libitum-fed (AL) group." (PMID 31927537, 2020). "IL-6 creates insulin resistance in the liver and enhances the hepatic synthesis of acute phase proteins such as CRP and fibrinogen." (PMID 32466598, 2020). "Homeostasis model assessment of insulin resistance (HOMA-IR) and interleukin-6 (IL-6) levels were determined to elucidate the mechanism underlying the prevention and improvement of obstructive pulmonary diseases." (PMID 33201904, 2020). "What is more, increased release of tumor necrosis factor α (TNF-α), interleukin 6 (IL6), and monocyte chemotactic protein 1 are all found to be responsible for the development of insulin resistance." (PMID 33042976, 2020). "Systemically, the high serum concentrations of IL-6, IL-1β, and TNF-α increase insulin resistance and cause endothelial dysfunction, priming the vascular system to the development of diabetes-related diseases, including systemic arterial hypertension." (PMID 32903730, 2020). "As with IL-6, TNFα levels positively correlate with adiposity, BMI, insulin levels, and insulin resistance." (PMID 32158768, 2020). "Like IL-6, increased levels of TNFα have also been shown to induce insulin resistance by impairing insulin signaling and glucose uptake in vivo." (PMID 33312199, 2020). "Increased levels of proinflammatory cytokines such as tumor necrosis factor-α, interleukin-6, and interleukin-8 were documented in people with diabetes or insulin resistance." (PMID 32907593, 2020). "IL-6 has been identified as a key mediator of inflammation, immune response, and glucose metabolism; it is the basis of insulin resistance in patients with T2DM." (PMID 33134394, 2020). "In the chronic low-grade inflammation, that is closely related with insulin resistance, other pro-inflammatory cytokines including interleukin-6 (IL-6), interleukin-1 (IL-1), and C-reactive protein are also involved." (PMID 33114725, 2020). "Meanwhile, activated PPARβ/δ prevents IL-6-induced insulin resistance by inhibiting the signal transducer and activator of transcription 3 pathway in adipocytes, which was enhanced in PPARβ/δ-null mice." (PMID 33083492, 2020). "Chronically elevated levels of IL-6 have been shown to decrease hepatic insulin sensitivity in vitro, to induce hyperinsulinemia in mice and to mediate insulin resistance in murine muscle tissue." (PMID 33178196, 2020). "Elevated levels of proinflammatory cytokines, such as IL-6, in the blood have been detected in individuals with insulin resistance." (PMID 33053742, 2020). "The multiple linear regression models found that the behavioral variables, BF%, insulin resistance, and hs-CRP were linearly associated with the inflammatory biomarkers TNF-α, IL-6, and leptin." (PMID 32694929, 2020). "Hyperglycemia is accompanied by an up-regulated expression of TNF-α, interleukin (IL)-1β, IL-6, and IL-18, which contribute to insulin resistance by both JNK and the IKKβ/NF-kβ pathway." (PMID 32431669, 2020). "Moreover, in the second trimester, in addition to the positive associations of IL-6 and leptin with insulin resistance, NGF was closely related to glucose metabolism, insulin resistance and pancreatic β cell function and might be a protective factor in the pathological process of GDM." (PMID 33292292, 2020). "In fact, these M1 macrophages that are activated within the adipose tissue have been identified to be a major source of circulating TNFα and IL-6 during obesity, insulin resistance, and T2D." (PMID 32183037, 2020).
Insulin resistance (continued). "LPS is the activator of pro-inflammatory cytokines, such as TNF-α, IL-1β, and IL-6, contributing to the development of insulin resistance." (PMID 33329010, 2020). "IL-6 plays a direct role in insulin resistance in skeletal muscles as well as in the liver due to the defects in IRS phosphorylation resulting in decreased gluconeogenesis and increased glycogenolysis." (PMID 32047529, 2020). "Even though LPS-induced steatosis is characterized by hepatic insulin resistance and the higher expression of tumor necrosis factor-α, IL-1 and IL-6, similar to the high-fat diet model, there are also some features that distinguish it from common NAFLD models." (PMID 32284043, 2020). "Interleukin family cytokines such as IL-6, IL-1β, and IL-18 regulate steatohepatitis progression through hepatic apoptosis, insulin resistance, and induce inflammation via activating NF-κB pathways." (PMID 33603757, 2020). "Pro-inflammatory cytokines such as IL-6 and TNF-α are implicated to promote insulin resistance by interfering with the insulin signaling pathway, leading to the pre-clinical manifestation of T2DM." (PMID 32694996, 2020). "The longstanding assertion that IL-6 leads to insulin resistance has been challenged by the discovery of IL-6’s actions in muscle." (PMID 32878032, 2020). "Although a study of the effect of dietary coconut oil on systemic inflammation has not been conducted, MCT fed to obese male mice has been shown to ameliorate insulin resistance and systemic inflammation approximated by IL-6 serum levels." (PMID 32190298, 2020). "Within the BMI groups, TG, TG/HDL and TG/HDL + IL-6 were the best predictors of insulin resistance in normal weight, overweight and obese subjects respectively." (PMID 32679640, 2020). "IL-6 can restore this imbalance and play an important role in the development and progression of insulin resistance." (PMID 31218568, 2019). "These phenomena are accompanied by abnormal release of FA, adipokines, and proinflammatory molecules including TNFα, interleukin (IL)-6, and IL-1β which, by acting on target organs, induce insulin resistance and favor the onset of type 2 diabetes." (PMID 31781039, 2019). "Neutralization or knockdown of inflammatory mediators, including TNF-α and IL-6, are protective against insulin resistance in obese rodents." (PMID 31075962, 2019). "In support of this argument, TNF-α, IL-6, IL-8, CCL2, CCL4, CCL5, and CCL19 were found to be implicated with metabolic inflammation or insulin resistance in various tissues and organs." (PMID 31718015, 2019). "The presence of inflammatory infiltrate in the hepatic tissue promotes cytokine and chemokine secretion, such as tumor necrosis factor a (TNF-a) and interleukin 6 (IL-6), which induce insulin resistance." (PMID 31482944, 2019). "Several adipokines like resistin, adiponectin, lipokolin-2 and IL-6 contribute to the development of insulin resistance, type 2 diabetes and cardiovascular diseases." (PMID 30674322, 2019). "Increased IL-6 levels disturb the glucose metabolism and contribute to the development of insulin resistance." (PMID 30674322, 2019). "Resistin is a pro-inflammatory adipokine, in addition it regulates insulin resistance and inflammation via IL-6 and TNF secretion from macrophages." (PMID 31788033, 2019). "Prenatal exposure to IL-6 in early and late pregnancy can lead to long-term adverse effects including insulin resistance, elevated stress response, hypertension, and dysregulation of hypothalamic–pituitary–adrenal axis activity during adulthood." (PMID 31739567, 2019). "Specifically, IL-6 is able to induce insulin resistance in both liver and adipocytes through reduction of phosphorylation of the insulin receptor substrate (IRS), or by transcription inhibition of the IRS." (PMID 31370223, 2019). "It is reported that proinflammatory cytokines TNF-α and IL-6 produced by HFD were able to induce insulin resistance." (PMID 31861309, 2019).
Insulin resistance (continued). "In contrast, chronic administration of IL-6 has been found to induce insulin resistance, suppress glucose transport, and reduce insulin-induced lipogenesis." (PMID 31736870, 2019). "In normal-weight subjects, a high level of interleukin 6 is associated with insulin sensitivity, although as fat mass increases, interleukin 6 contributes to insulin resistance." (PMID 30457109, 2019). "Inflammation in NAFLD is one of the main causes of insulin resistance with inflammatory markers such as TNF-α and IL-6 suppressing insulin receptor signaling, thus blocking the action of insulin in hepatocytes." (PMID 30764536, 2019). "In turn, IL-6 causes the PKCδ-dependent phosphorylation of IRS-1 in muscles, which leads to insulin resistance." (PMID 31363792, 2019). "IL-6 triggered hepatic insulin resistance attributable to the “mammalian target of rapamycin” in a manner involving the STAT3-SOCS3 pathway." (PMID 31396538, 2019). "In T2DM rats, UC-MSCs can alleviate insulin resistance in part via production of IL-6 that elicits M2 polarization." (PMID 31455405, 2019). "As a result of this inflammation, the synthesis of pro-inflammatory cytokines (TNF-alpha, IL-6, and IL-1β) becomes increased and insulin resistance develops." (PMID 30881343, 2019). "To test the relation of inflammatory markers and adipose tissue insulin resistance, we first tested simple correlations of adipose insulin resistance indices and IL-6/CRP." (PMID 30637483, 2019). "It has been shown that increased concentrations of IL-1β and IL-6 contribute to the weakening of insulin signaling, presumably leading to insulin resistance." (PMID 31707362, 2019). "The present investigation suggests a significant link between intraocular IL-6 levels and two systemic factors—insulin resistance (represented as HOMA-IR) and smoking." (PMID 31396410, 2019). "EVs harvested from adipose tissue from obese ob/ob mice have been found to induce macrophage activation, proinflammatory cytokine release such as IL-6 and TNFα, as well as promoting insulin resistance when injected into wildtype mice." (PMID 30736459, 2019). "In this analysis, concentrations of IL-6 were positively related with the indices of adipose tissue insulin resistance." (PMID 30637483, 2019). "It is known that, in obese subjects, chronic inflammation is observed, with increased levels of proinflammatory cytokines, including IL-6 and tumor necrosis factor-n (TNFα), which increase insulin resistance." (PMID 31001554, 2019). "Pro-inflammatory cytokines, including interleukins 6 and 8 (IL-6 and IL-8) and tumor necrosis factor-α (TNFα), are key players in the onset of insulin resistance." (PMID 31849810, 2019). "M1 macrophages are host-defense cells that kill pathogens and secrete proinflammatory cytokines such as TNF-α and IL-6, both of which contribute to insulin resistance." (PMID 31577826, 2019). "Cytokines, including FasL, TNF α, and IL-6, play important roles in the induction of β-cell apoptosis as well as insulin resistance." (PMID 30953496, 2019). "Pleiotropic IL-6, in 1/3 derived from adipose tissue, induces hyperglycaemia, hyperlipidaemia and insulin resistance in humans and animals; however, is still described ambiguously in the context of osteoresorption." (PMID 31500356, 2019). "The aim of our study was to assay circulating interleukin-15 (IL-15) and interleukin-6 (IL-6) levels and insulin resistance measured by two different methods in newly diagnosed autoimmune diabetes (AD) patients, their I° relatives, and healthy controls." (PMID 31772933, 2019). "WAT M1 macrophages generate pro-inflammatory cytokines, such as tumor necrosis factor α (TNFA-α) and interleukin 6 (IL6), thus contributing to the induction of insulin resistance." (PMID 31614949, 2019).
Insulin resistance (continued). "We used the model to simulate the dynamics of gene expression induced by different combinations of the five input signals, i.e. ER stress, oxidative stress, and cytokines (TNF α, FasL, IL-6), which serve as triggers for insulin resistance and β-cell apoptosis." (PMID 30953496, 2019). "Insulin resistance and smoking status impacted intraocular levels of IL-6, while intraocular VEGF levels were influenced by Lp-A." (PMID 31396410, 2019). "IL-6 is a key player in tissue inflammation and insulin resistance, and was observed in higher serum concentrations in PE/HDP patients." (PMID 31683992, 2019). "For example, IL-1, IL-6, and TNF-alpha that are linked to periodontal disease progression, are associated to insulin resistance too." (PMID 31835888, 2019). "TNF-α and IL-6 are the most important pro-inflammatory mediators responsible for inducing insulin resistance in adipocytes and peripheral tissues." (PMID 30871060, 2019). "In a study on 671 children and adolescents with a mean age of 13.3 ± 2.7 years, higher levels of the pro-inflammatory cytokine interleukin-6 (IL-6) were directly related to adipose tissue insulin resistance." (PMID 31052376, 2019). "As a large amount of FFA, resistin, TNF-α, interleukin 6 and other compounds released by oversized adipose tissue can produce insulin resistance." (PMID 31801571, 2019). "Our study corroborates further by establishing a significant correlation between insulin resistance and intraocular IL-6—a cytokine so crucial for initiation and progression of DR." (PMID 31396410, 2019). "M1 macrophages secrete the proinflammatory cytokines TNF-α, IL-1β, and IL-6, which promote insulin resistance and the accompanying deleterious metabolic effects, as well as synthesis of C-reactive protein." (PMID 31015797, 2019). "It is assumed that TNFα and IL-6 are to varying degrees the driving force behind insulin resistance and especially IL-6 can be regarded as a marker for the metabolic syndrome." (PMID 30759730, 2019). "Adiponectin can act as an insulin sensitizer, while pro-inflammatory cytokines, such as TNF-α and IL-6, contribute to insulin resistance." (PMID 31731774, 2019). "In the insulin resistance control group, the expression levels of IL-6, RORγt, and IL-17 increased, whereas those of IL-10, FoxP3, and CD4+CD25+Treg decreased." (PMID 31218568, 2019). "Collectively, these then produce greater amounts of pro-inflammatory cytokines, namely IL-1β, IL-6, and TNFα as well as chemokines such as MCP-1, which are causally associated with insulin resistance, dyslipidemia, and metabolic disease." (PMID 30736459, 2019). "While acute treatment of myocytes or intravenous infusion of IL-6 to healthy humans increases basal and insulin-stimulated glucose uptake by myocytes and improves whole body insulin sensitivity, chronic action of IL-6 induces insulin resistance." (PMID 30699907, 2019). "Expression of the two most important pro-inflammatory cytokines, TNF-α and IL-6, is enhanced by the elevation of fat and insulin resistance in the body." (PMID 31597283, 2019). "The most important role of MCP-1 is to regulate the migration and infiltration of monocytes and macrophages, but it can also contribute to insulin resistance, acting together with other mediators such as IL-6 and TNF-α." (PMID 31438590, 2019). "TNF-α and IL-6 not only drive keratinocyte proliferation and differentiation but also increase insulin resistance and promote proinflammatory cytokines release." (PMID 29546055, 2018). "High levels of both IL-6 and TNF-α have been reported to be associated with insulin resistance in the adipocytes, hepatocytes and myocytes." (PMID 30914847, 2018). "PGRN plays a role in adipose tissue, recruiting monocytes and promoting interleukin-6 (IL-6) expression, which favors inflammation and insulin resistance." (PMID 29499059, 2018).